CD58 (CD58 molecule)
Diseases named in the same sentence as CD58 in open-access papers (continued):
Sharing a sentence is not in itself a finding about the gene and the disease.
tumor (continued). "A recent study reported that CD58 was overexpressed in HCC tissues and positively correlated with tumor-infiltrating immune cells." (PMID 37573318, 2023). "While NK cell adhesion to tumor cells is mediated by integrin αLβ2, NK cells use integrin αMβ2 and receptor CD2 to interact with ICAM-4 and CD58 on iRBC, respectively." (PMID 37939134, 2023). "Although this experiment provided insights into the potential impact of the CMTM6-CD58 axis on tumor cell survival in vivo, further investigation is needed to understand how CMTM6 and CD58 expression on tumor cells modulates T cell activities." (PMID 37683639, 2023). "Results indicated that among the four subgroups of MB, nine kinds of infiltrating immune cells (such as CD14, Regulatory T (Treg), CD58, CD8, and CD19) were statistically significant in the degree of tumor infiltration (p < 0.001)." (PMID 35967388, 2022). "CD2 and CD244 are members of the CD2 family of proteins and interact with the partner proteins CD58 and CD48 either on other T cells (homotypic) or tumor cells (heterotypic)." (PMID 35881486, 2022). "Therefore, CD58 might be an effective tumor marker for PDAC." (PMID 34193136, 2021). "By comparing the tumor tissues and corresponding normal samples using GEPIA, the results demonstrated that CD58 level was reduced in kidney chromophobe cancer (KICH)." (PMID 34193136, 2021). "CD112 (Nectin-2, PVRL2) and CD155 (Necl5, PVR) bind CD226 (DNAM-1), which potentiates in vitro the cytotoxicity of NK cells against a wide range of tumor cells; CD58 (LFA-3) binds CD2 and its co-engagement with ICAM-1 increases NK response." (PMID 26106390, 2015). "They showed a uniform population of CD45−, CD56+, CD9+, CD81hi, GD2+ tumor cells with heterogeneous expression of CD57−/+ and CD58+/++; CD90 was positive in all but one tumor, whereas CD271 was partially expressed in only one tumor." (PMID 23472067, 2013). "In the CAR system, previous studies have also demonstrated that the absence of CD58 on tumor cells compromises IS integrity." (PMID 40615696, 2025). "As the tumor cells express ICAM1, CD58, and CD80, all of which could contribute to TcE-independent adhesion, we used human serum IgGs as a negative control for TcE-specific effects." (PMID 40445758, 2025). "Additionally, dynamic IPA site usage was observed in well-known tumor suppressor genes, including TSC1, HSD17B2, CD58, RUNX1 and INPP4B." (PMID 41218079, 2025). "Furthermore, the mechanism of expression regulation between CD58 and PD-L1 revealed that for CD58-PD-L1+ tumor cells, the strategy of co-targeting CD58 with PD-1/PD-L1 blockers may be more beneficial to activate T-cell killing, thus overcoming drug resistance in this tumor type." (PMID 40365344, 2025). "Notably, the CD2–CD58 interaction, where CD2 is expressed by T cells and CD58 by tumor cells, was significantly elevated, suggesting a key immunoregulatory function." (PMID 40859981, 2025). "Since there is no mouse homolog of CD58 in pre-clinical mouse models, syngeneic models cannot be used to investigate tumor cells-immune cells interactions and responses to immune checkpoint inhibitors in vivo." (PMID 38589927, 2024). "We compared the protein levels of HSPA4, ALKBH5 and CD58 in tumor tissues between responders and non-responders by using mfIHC." (PMID 38589927, 2024). "Expression of CD58 and ligation to CD2 is required for anti‐tumour immunity." (PMID 39054569, 2024). "Increased HSPA4 (P < 0.01), ALKBH5 (P < 0.05) and decreased CD58 (P < 0.05) were observed in tumor tissues of responders compared with non-responders." (PMID 38589927, 2024). "Secondly, we unveil a novel mechanism of immune evasion of GC cells: HSPA4 overexpression in GC cells decreases CD58 via ALKBH5/CD58 pathway, activates PD1/PDL1 axis, decreases cytotoxicity and infiltration of CD8+ T cells and induces tumor immunosuppressive microenvironment." (PMID 38589927, 2024).
tumor (continued). "Despite the suggested role of the CD2‒CD58 axis in preventing T-cell dysfunction, how CD2 costimulation regulates tumor immunity remains unknown." (PMID 39349829, 2024). "To evaluate whether ALKBH5 could regulate CD58, we first examined the protein level of ALKBH5 in GC cell lines and found that it was upregulated in GC cell lines compared with pooled non-tumor gastric tissues." (PMID 38589927, 2024). "Collectively, these findings provide fundamental insights into CD58 regulation, uncover a shared regulator of stimulatory and inhibitory immune checkpoints, and highlight the importance of tumor-intrinsic CMTM6 and CD58 expression in antitumor immune responses." (PMID 37683639, 2023). "In HRSdx cells, the decrease in HLA-DR expression could favor the escape from immune system recognition and the increase in CD58, by improving the interactions with CD40L+CD2+ rosetting T cells, and could support tumor cell survival." (PMID 38067159, 2023). "We found that, in addition to interacting with CD2, CD58 was co-expressed and physically interacted with HOXB family genes (HOXB2, HOXB3, and HOXB5), AKAP12, CLIC1, CPNE3, etc., which were reported to be involved in tumor initiation and progression." (PMID 34193136, 2021). "The absence of CD58 expression is a common feature of BL, which helps tumor cells escape immunological surveillance." (PMID 34168659, 2021). "Moreover, RMS cases were also CD45−, CD56+lo, CD90+ and CD57−; two expressed CD81+, CD9+ and CD58+ and one was partially positive for CD99 (40% of tumor cells ), a phenotypic pattern which was specific for this tumor subtype." (PMID 23472067, 2013). "Unlike the specific case where a lack of CD58 leads to a total loss of CD58-CD2 axis function, in more common scenarios where tumor cells express CD58, the dynamic variation in CD2 expression levels on T cells becomes the primary determinant affecting the axis’s function." (PMID 40615696, 2025). "Notably, CD58 loss—rather than CD2 deficiency—is a primary mechanism of axis disruption, leading to impaired T-cell cytotoxicity and tumor immune evasion." (PMID 41438981, 2025). "Furthermore, the absence of in vivo validation limits our understanding of CD58’s function within the complex tumor microenvironment." (PMID 41438981, 2025). "Correspondingly, the absence of CD58 on tumor cells also significantly hindered IS formation." (PMID 40615696, 2025). "We further investigated whether CD58 silencing has anti-tumor effects in vivo, Huh7 cells with or without CD58-knockdown were injected subcutaneously into the right and left flanks of nude mice." (PMID 37573318, 2023). "It has been shown that CD58/CD2 interaction stimulated the synergistic secretion of CXC chemokine ligand 8 (CXCL-8/IL-8) of human intestinal CD3 + TCRαβ + CD8+ intraepithelial lymphocytes (IELs), and CXCL-8 induces cell proliferation and migration, promoting tumor cell growth in CRC." (PMID 37836662, 2023). "From a diagnostic perspective, patients can be stratified based on CD58 expression and monitored to determine whether escape from adoptive cell therapy is accompanied by the expansion of CD58-negative tumor cells." (PMID 35881486, 2022). "Therefore, the function of CD58 in tumor cells is not simple and isolated, but complex and diverse, and needs to be further investigated in depth." (PMID 34168659, 2021). "Additionally, we also found that CD58 might act as an immune checkpoint gene in HCC via PD1/CTLA4 pathways and regulate the levels of tumor-infiltrating immune cells in HCC tissues, which might be an immunotherapeutic target in HCC." (PMID 34423049, 2021).
tumor (continued). "Interestingly, our research indicated that CD58 might act as an immune checkpoint gene in HCC and regulate the levels of tumor-infiltrating immune cells in HCC tissues, which might be an immunotherapeutic target in HCC." (PMID 34423049, 2021). "CD58 is involved in the immune recognition of the tumour cells via binding of the CD2 receptor expressed by most cytotoxic CD8+ T cells and NK cells: its downregulation further represent an immune escape mechanism of HL tumour cells, at least in the clinically aggressive disease." (PMID 34298847, 2021). "Additionally, reduction of CD58 expression by shRNA to the same level as observed in CMTM6-knockout cells resulted in a slightly more pronounced attenuation of T cell activation and improved the tumor cell survival compared to that observed in CMTM6-knockout cells." (PMID 37683639, 2023). "In hematologic malignancies, there appear to be other adhesion molecules that stabilize the CAR-T/tumor interaction, namely the CD2/CD58 axis, that are not regulated by IFNgR signaling." (PMID 38052854, 2023). "Also, Tregs from NI ad I TDLN share CD58, ITGAM, MCAM, CEACAM4, SELPLG, and HMMR expression, which could ensure recirculation among TDNLs; and Tregs from I TDLN and tumor Tregs share ICAM1 expression, which could be responsible for the migration among tissues with presence of tumor cells." (PMID 32601304, 2020).
cancer (32 papers, 2011 to 2025). A tumor composed of atypical neoplastic, often pleomorphic cells that invade other tissues. "Pan-cancer analysis revealed that CD58 was associated with key immune regulatory factors, including PD-L1, chemokines (CCL5, CXCL9, CXCL10)." (PMID 41438981, 2025). "To elucidate CD58’s immunoregulatory functions, we examined its associations with immune-related genes—including chemokines, chemokine receptors, immune checkpoints, immunostimulators, and immunosuppressors—across 33 cancer types in the TCGA dataset." (PMID 41438981, 2025). "Importantly, STARs would remain susceptible to immune evasion by cancer cells losing expression of CD58 and/or ICAM-1." (PMID 36598945, 2023). "To systematically characterize CD58’s role across malignancies, we analyzed its mRNA expression in 33 cancer types from TCGA database." (PMID 41438981, 2025). "The immunomodulatory drug lenalidomide or the epigenetic modulator EZH2 inhibitor (EPZ6438, GSK126) have been observed to restore CD58 expression in cancer cells." (PMID 40365344, 2025). "Future research should prioritize the development of therapeutic strategies, such as CD2 agonists, to restore CD58 expression in hematological tumors or to circumvent the CD2-CD58 axis to target CD58- immuno-resistant cancer cells." (PMID 40365344, 2025). "CD2, CD48, and CD58, closely related to the immunoglobulin superfamily, are involved in T cell responses to cancer cells." (PMID 37904707, 2023). "Collectively, these results establish CMTM6 as a regulator of CD58 protein levels in various cancer types and in primary human DCs." (PMID 37683639, 2023). "Drugs such as the immunomodulatory drug lenalidomide or inhibitors of the epigenetic modulator EZH2 are promising leads, since they have been shown to restore CD58 expression in cancer cells." (PMID 35881486, 2022). "Analysis from Oncomine, a powerful data analysis platform with 715 datasets and 86,733 samples, found that CD58 was abnormally expressed in multiple human cancers." (PMID 34193136, 2021). "By Day 21, all genes tested but one (CD58 in Colo201) continued to show significant down regulation in cancer cell lines compared to normal colon." (PMID 28622390, 2017). "The treated cancer cells showed a significant upregulation of these genes compared to Mock on Day 3 after treatment, except for CD58 in CaCo2." (PMID 28622390, 2017). "Additionally, we evaluated the clinical relevance of CMTM6 and CD58 protein expression in human cancers and explored their potential implications for ICB therapies." (PMID 37683639, 2023). "Furthermore, the correlation between CD58 and the cancer stem cell (CSC)-related, epithelial–mesenchymal transition (EMT)-related, and immune-related markers were detected." (PMID 34193136, 2021). "TRICOM poxviral vaccine encoding CEA and three costimulatory molecules B7.1, inter-cellular adhesion molecule-1 (ICAM-1), and lymphocyte function-associated antigen 3 (LFA-3 or CD58), was used to treat patients with CEA-expressing cancers in combination with IFN-α-2b." (PMID 30257488, 2018). "Besides immunoglobulin heavy chains, T-cell receptors (such as TCR-a and TCR-b), immunoglobulin -like cell adhesion molecules (such as CD47, CD54, CD58) were also found to be expressed in cancer cells." (PMID 23133595, 2012). "Moreover, CD58 is previously shown to be involved in self‐renewal ability of cancer cells, and this could be a potential mechanism via which it mediates chemoresistance in PDAC." (PMID 37533202, 2023). "The broad expression of CD58, CD112 and CD155 on cancer cells provided a rationale to assess CD2::CD28 and CD226::CD28 chimeras." (PMID 29707134, 2018). "CD58 also harbored a higher-than-expected number of nonsynonymous mutations and homozygous deletions in DLBCL and the pan-cancer primary cohort." (PMID 37165135, 2023).
cancer (continued). "While this latter link provides only correlative evidence, we note that the frequent concurrent expression of CD58 and CMTM6 in human tumors provides support for the notion that the mechanistic effects here modeled in vitro and in a humanized mouse model may also be at play in human cancer." (PMID 37683639, 2023).
infection (12 papers, 2005 to 2023). The state of being infected such as from the introduction of a foreign agent such as serum, vaccine, antigenic substance or organism. "Although levels of expression of CD58 (LFA3), an adhesion molecule, and the cytokine IL6 altered most rapidly following exposure to EBV, expression of CD58 on CD23+ cells was the earlier marker of infection with EBV." (PMID 21352549, 2011). "Indeed this rapid up-regulation of CD58 may be part of the immune response alerting the host to infection with EBV." (PMID 21352549, 2011). "We found no change in CD112, CD155, MICA/B, or CD58 (data not shown) expression following dl922-947 infection." (PMID 32195317, 2020). "Interestingly, UL148 was also recently identified to prevent surface presentation of CD58 (LFA-3), a co-stimulatory ligand for natural killer cells and T-cells, and to strongly contribute to the induction of the unfolded protein response (UPR) during infection." (PMID 30544948, 2018). "It is worth noting that infection of endothelial cells with KSHV results in down-regulation of MHC class I, PE-CAM (CD31), and ICAM-1 (CD54), but not LFA-3 (CD58) or Fas (CD95), and the viral genes K3 and K5 have been demonstrated to regulate this outcome." (PMID 18787698, 2008).
hematological cancer (3 papers, 2016 to 2025). "From a clinical perspective, the loss of CD58 has been associated with relapse and immune escape in hematological cancers and thus has broader impact beyond just CAR T cell therapy, as we have outlined here." (PMID 35881486, 2022). "In summary, CD58 expression in hematological tumors is frequently related to treatment response and longer survival, while CD58 loss contributes to immune evasion, facilitates the emergence of resistance to immunotherapies like CAR-T cell therapy, and indicates a poorer prognosis." (PMID 40365344, 2025). "In this paper, we will deeply describe the function of CD58 in immune cells, its impact on hematological tumors, and its role in CAR cell therapy and other immunotherapies." (PMID 40365344, 2025). "All of these suggest that the CD58 antigen has excellent potential to help treat hematologic cancers." (PMID 40365344, 2025).
bacterial infection (2 papers, 2018 to 2024). "Blockade or knockdown of Cd58 and Cd2 dramatically impaired the activation of antigen-specific Cd4+ T and mIgM+ B cells, followed by the inhibition of antibody production and host defense against bacterial infections." (PMID 29904386, 2018). "By knockdown and blockade of Cd58 or Cd2, the activation of antigen-specific Cd4+ Th cells was significantly impaired, mIgM+ B cell activation and Ab (IgM) production were inhibited, and defense against bacterial infections post-vaccination was diminished." (PMID 29904386, 2018).
neurodegenerative disease (1 paper, 2025). A disorder of the central nervous system characterized by gradual and progressive loss of neural tissue and neurologic function. "Twenty-seven of these associations are known disease loci reported in GWAS, including APOE, MME, CD2AP, CD33 and IL34 for AD, and CD40, CD58, EVI5, IL7R and STAT3 for MS, and 23 associations represent previously unreported genetic associations with neurodegenerative diseases." (PMID 40037332, 2025).
CD58 also shares sentences with these, for which no sentence is quoted: psoriasis (12 papers); blood cancers (2); candidiasis (2); colorectal tumor (2); hematologic malignancies (2); lupus (2); nasopharyngeal carcinoma (2); thyroid cancer (2); type 1 diabetes (2); adult T-cell leukemia/lymphoma (1); bladder cancer (1); brain tumor (1); cervical squamous cell carcinoma (1); cholangiocarcinoma (1); Chronic Lymphocytic Leukemia (1); endometrial cancer (1); endometriosis (1); esophageal carcinoma (1); follicular lymphoma (1); Granuloma (1); Graves disease (1); Hashimoto’s disease (1); head and neck squamous cell carcinoma (1); herpesvirus infection (1); HIV-1 infection (1); kidney chromophobe (1); leiomyoma (1); liver cirrhosis (1); lung carcinoma (1); lung squamous cell carcinoma (1).
A further 22 diseases each share a sentence with CD58 in 1 paper.